OR5T1 (olfactory receptor family 5 subfamily T member 1)
Description:
Odorant receptor.
Synonyms: OR5T1P; OR11-179
Tractability: Antibody: UniProt places it where antibodies can reach, with medium confidence; UniProt predicts a signal peptide or a membrane-spanning region; its Gene Ontology location is reachable by antibodies, with medium confidence.
Gene: Protein-coding gene on chromosome 11 (56,274,154 to 56,276,819, forward strand). Ensembl gene ENSG00000181698.
Subcellular location: Cell membrane
Pathways (Reactome):
Sensory Perception: Expression and translocation of olfactory receptors
Gene Ontology:
Molecular function: olfactory receptor activity; G protein-coupled receptor activity
Biological process: G protein-coupled receptor signaling pathway; sensory perception of smell; detection of chemical stimulus involved in sensory perception of smell
Cellular component: plasma membrane; membrane
Genetic constraint (gnomAD): Loss-of-function variants: 8 observed, 7.13 expected, observed/expected ratio (o/e) 1.12, 90% interval 0.65 to 1.82. That is too few expected variants to judge how well the gene tolerates losing a copy. Missense variants: 380 observed, 338.07 expected, observed/expected ratio (o/e) 1.12, 90% interval 1.03 to 1.22. Synonymous variants: 138 observed, 123.87 expected, observed/expected ratio (o/e) 1.11, 90% interval 0.97 to 1.28.
Homologues: Orthologues: chimpanzee OR5T1 (97% identical), mouse Or5t17 (74% identical), mouse Or5t9 (74% identical), rat Or5t5 (74% identical), mouse Or5t5 (74% identical), rat Or5t9b (73% identical), rat Or5t5b (73% identical), Caenorhabditis elegans ser-5 (17% identical), zebrafish adra1ab (16% identical). Paralogues in human: OR5T3 (80% identical), OR5T2 (74% identical), OR13F1 (43% identical), OR56A1 (29% identical), OR56A4 (29% identical), OR56A3 (28% identical), OR56A5 (28% identical), ADRA2A (20% identical), ADRA2B (19% identical), ADRA1B (19% identical), ADRA2C (19% identical), ADRA1D (18% identical), and 6 more.